DKK1 (dickkopf Wnt signaling pathway inhibitor 1)
Diseases named in the same sentence as DKK1 in open-access papers (continued):
Sharing a sentence is not in itself a finding about the gene and the disease.
metabolic disease (3 papers, 2014 to 2025). A congenital disorder (due to inherited enzyme abnormality) or acquired (due to failure of a metabolically important organ) disorder resulting from an abnormal metabolic process. "The levels of DKK1 in patients with PCOS and IR are significantly elevated, revealing a potential relationship between DKK1, PCOS, and metabolic disorders, and suggesting that DKK1 may serve as a biomarker associated with PCOS and metabolic disorders." (PMID 41320970, 2025). "Dickkopf1 (DKK1) is a protein with established links to metabolic diseases." (PMID 41320970, 2025). "We therefore speculate that DKK1 may act as a negative regulator of metabolic disorders and insulin sensitivity." (PMID 41320970, 2025). "High levels of DKK1 may indicate severe IR and metabolic disorders in PCOS women." (PMID 41320970, 2025). "We propose that DKK1 could be a biomarker associated with PCOS and metabolic disorders." (PMID 41320970, 2025). "In conclusion, our study underscores the substantial elevation in DKK1 levels in PCOS patients and the potential relationship between DKK1 and PCOS and metabolic disorders." (PMID 41320970, 2025). "In conclusion, our study highlights the significant increase in DKK1 levels in PCOS patients and reveals the potential relationship between DKK1 and PCOS and metabolic disorders." (PMID 41320970, 2025). "To elucidate the interplay between DKK1, metabolic disorders, and IR in PCOS patients, we concurrently measured the levels of circulating DKK1 and Adipoq, an insulin‐sensitive molecule." (PMID 41320970, 2025). "While our study has made a new discovery regarding the significance of circulating DKK1 levels in PCOS and metabolic disorders, it is subject to some limitations." (PMID 41320970, 2025). "Our finding suggests that DKK1 may be a potential therapeutic and diagnosis candidate for NAFLD and metabolic disorder progression." (PMID 36410795, 2023). "Therefore, DKK1 may be a novel target for drug development for NAFLD and metabolism disorders." (PMID 36410795, 2023). "Second, the upregulation of DKK1 may not be exclusive to PCOS and IR but also occur in other metabolic disorders characterized by chronic inflammation and IR, thereby diminishing its diagnostic specificity." (PMID 41320970, 2025).
hematological disorders (2 papers, 2018 to 2021). "In other studies, reduced Dkk1 serum levels have been described in patients with hematological disorders and in post-menopausal women treated with high GC." (PMID 34229744, 2021).
Musculoskeletal diseases (2 papers, 2019 to 2024). "Our team has been dedicated to exploring the therapeutic potential of DKK1 inhibition for musculoskeletal disorders." (PMID 38773377, 2024). "Musculoskeletal diseases: A strategy that has been proposed to treat musculoskeletal diseases via the WNT pathway is to develop inhibitors for WNT antagonists that are relevant to bone development, mainly DKK1 and sclerostin." (PMID 31382613, 2019).
bacterial infection (1 paper, 2024). "Using an ACLF mouse model combining chronic liver injury, acute hepatic insult, and bacterial infection that phenocopies some of the key clinical features of ACLF patients, we tested the MSC-protective effects of Nrf2/DKK1 co-stimulation." (PMID 38529014, 2024).
colon polyp (1 paper, 2011). "Consequently, we evaluated serum 25(OH) D levels, vitamin D receptor (VDR) polymorphisms and the methylation status of the tumor suppressor gene dickkopf homolog 1 (DKK1) as risk factors for colon polyp in this population." (PMID 22022386, 2011).
retinopathy (1 paper, 2014). "To further investigate potential DKK1 and DKK2 involvement in pathological angiogenesis, we applied an oxygen-induced retinopathy (OIR) model to DKK1 Tg and DKK2 Tg mice." (PMID 24091497, 2014). "We further observed that DKK1 diminished retinal vessel density and increased avascular area in an in vivo murine model of oxygen-induced retinopathy, whereas DKK2 showed opposite results." (PMID 24091497, 2014).
DKK1 also shares sentences with these, for which no sentence is quoted: multiple myeloma (78 papers); Wilms tumor (8); renal cell carcinoma (6); kidney disease (5); van Buchem disease (5); Cerebral ischemia (4); chronic periodontitis (4); coronary artery (4); type 1 diabetes mellitus (4); Barrett esophagus (3); diabetic retinopathy (3); head and neck cancer (3); Lewis lung carcinoma (3); Oligodontia (3); serous ovarian cancer (3); age (2); asthma (2); calcification (2); cerebral infarction (2); chronic hepatitis B (2); colon adenocarcinoma (2); colon adenoma (2); fracture (2); gallbladder cancer (2); gastroesophageal junction adenocarcinoma (2); hilar cholangiocarcinoma (2); hyperparathyroidism (2); intracerebral haemorrhage (2); neurological disorders (2); small cell lung carcinoma (2).
A further 98 diseases each share a sentence with DKK1 in 1 paper.